HTT (huntingtin)
Diseases named in the same sentence as HTT in open-access papers (continued):
Sharing a sentence is not in itself a finding about the gene and the disease.
Huntington disease (continued). "Huntington's disease (HD) is an autosomal dominant neurodegenerative disorder resulting from polyglutamine expansion in the huntingtin (HTT) protein and for which there is no cure." (PMID 24926995, 2014). "Huntington's disease (HD) is a neurodegenerative autosomal dominate disorder caused by increased CAG repeats, this leads to increased accumulation of mutant huntingtin, and formation of intranuclear inclusions and eventually to brain damage." (PMID 25340651, 2014). "The study was designed to see how alterations in the huntingtin gene in a mouse model of Huntington’s disease would affect the perception and processing of almond odor, an evolutionarily conserved stimulus with high emotional and motivational valence." (PMID 25071696, 2014). "Huntington's disease (HD) is an autosomal dominant, progressive neurodegenerative disorder caused by expansion of CAG repeats in the huntingtin gene." (PMID 24955833, 2014). "Prevention of caspase-6 mediated cleavage of huntingtin has been shown to alleviate Huntington disease pathology in YAC transgenic mice." (PMID 24961702, 2014). "By electron microscopy, huntingtin inclusions produced by transiently transfected MCF7 cells or found in the brain of patients with Huntington disease show globular aggregates concentrated at the periphery or in the center of the inclusions, respectively." (PMID 24961702, 2014). "We found that Ryk is up-regulated in neurons expressing mutant huntingtin (HTT) in several models of Huntington's disease (HD)." (PMID 24960609, 2014). "Psychiatric and metabolic features appear several years before motor disturbances in the neurodegenerative Huntington’s disease (HD), caused by an expanded CAG repeat in the huntingtin (HTT) gene." (PMID 25271967, 2014). "Huntington disease (HD) is an inherited, fatal neurodegenerative disorder caused by a CAG repeat expansion in the huntingtin gene." (PMID 25207939, 2014). "In Huntington’s disease (HD), the ratio between normal and mutant Huntingtin (polyQ-hHtt) is crucial in the onset and progression of the disease." (PMID 25091984, 2014). "Perhaps the best-known polyQ disease is Huntington’s disease, characterized by the aggregation of the multi-functional huntingtin protein." (PMID 25258700, 2013). "In models of Huntington’s disease (HD), transcription of PGC-1α is repressed by mutant huntingtin, the protein that causes HD." (PMID 24093018, 2013). "Recently, ITSN1 was suggested to contribute to Alzheimer’s disease and to the aggregation of huntingtin during Huntington’s disease." (PMID 23936226, 2013). "This feature is shared by other protein accumulating disorders such as aggregates of Huntingtin protein, a prion-like protein that is seen in Huntington’s disease." (PMID 24340066, 2013). "In cellular models of Huntington's disease, miR-146a, miR-125b, and miR-150 are down regulated while miR-34b was elevated by the presence of mutant HTT protein." (PMID 24133413, 2013). "Huntington disease (HD) is caused by the expansion of a CAG repeat within the HD gene and the corresponding poly-glutamine track within the Huntingtin (HTT) protein." (PMID 23871671, 2013). "Transgenic upregulation of HSJ1a in a mouse model of Huntington's disease reduced huntingtin aggregation and improved neurological performance by reducing the ability of aggregated huntingtin to promote further aggregation." (PMID 24023695, 2013). "Huntington’s disease (HD) is characterized by motor dysfunction and cognitive decline, and is caused by an autosomal dominant expansion of CAG repeats in the Huntingtin (HTT) gene." (PMID 23936129, 2013). "The presence of huntingtin aggregates in the brain correlates strongly with functional deficits in individuals with Huntington’s disease (HD)." (PMID 23853712, 2013). "In studies on Huntington's disease pathogenesis, overexpression of mutant Huntingtin with 74 CAG repeats in HeLa cells leads to mitochondrial fragmentation and reduced ATP levels." (PMID 24288463, 2013).
Huntington disease (continued). "ThesiRNA technology was used to show that the inhibition of GAPDH expression leadsto a 45–50% reduction in the aggregation of mutant huntingtin, with a repeat of103 glutamine residues in a model of Huntington’s disease (HD)." (PMID 23819039, 2013). "HDAC4 reduction presents a novel strategy for alleviating the toxicity of huntingtin protein aggregation, thereby influencing the molecular pathology of Huntington's disease." (PMID 24302884, 2013). "In Huntington disease (HD), there is increasing evidence for a link between mutant huntingtin expression, mitochondrial dysfunction, energetic deficits and neurodegeneration but the precise nature, causes and order of these events remain to be determined." (PMID 24303051, 2013). "Specific silencing in cellular models has also been reported to SNPs targeting ataxin-7 in SCA7 and huntingtin in Huntington's disease." (PMID 23349684, 2013). "Huntington's disease (HD) is an autosomal dominant neurodegenerative disorder due to an extension of CAG repeat in the coding region of the Huntingtin gene." (PMID 24133419, 2013). "In Huntington's disease (HD) model, striatum and cortex of mice expressing full length endogenous mutant Huntingtin (Htt140q/140q) have higher activity of NADPH oxidase which generates ROS than in similar aged controls." (PMID 24288463, 2013). "Huntington’s disease (HD), a neurodegenerative disorder caused by an expanded CAG repeat in the huntingtin gene, impairs information processing in the striatum, which, as part of the basal ganglia, modulates motor output." (PMID 24961622, 2013). "Huntington’s disease (HD) is a dominantly inherited genetic disorder induced by an abnormal expansion of a CAG trinucleotide repeat at the 5′ terminal part of the Huntingtin (Htt) gene leading to a polyglutamine expansion in the Htt protein." (PMID 24167500, 2013). "Huntington Disease (HD) is a neurodegenerative disorder resulting from the expansion of polyglutamine stretch in the huntingtin protein (Htt)." (PMID 24330808, 2013). "Huntington's disease (HD) is an autosomal dominant, progressive and fatal neurological disorder caused by an expansion of CAG repeats in exon-1 of the huntingtin gene." (PMID 24086450, 2013). "The genome of the Bacterial Artificial Chromosome (BAC) transgenic mouse model of Huntington’s Disease (BAC HD) contains the 170 kb human HTT locus modified by the addition of exon 1 with 97 mixed CAA-CAG repeats." (PMID 24042107, 2013). "For example, Huntington disease (HD) is caused by an over 35 CAG trinucleotide repeat expansion, which results in a long mutant polyQ tract in the huntingtin protein." (PMID 24248062, 2013). "Huntington's disease (HD) is an inherited neurodegenerative disorder as a result of the expansion of a CAG trinucleotide repeat in the huntingtin gene (HTT)." (PMID 24069174, 2013). "An expansion of glutamine repeats in the N-terminal domain of the huntingtin protein leads to Huntington's disease (HD), a neurodegenerative condition characterized by the presence of involuntary movements, dementia, and psychiatric disturbances." (PMID 23423362, 2013). "Huntington disease (HD) is a neurodegenerative disorder, caused by CAG repeat expansion in the HTT gene, which is located on chromosome 4 and encodes huntingtin." (PMID 23405066, 2013). "We collected demographic and clinical data, conducted the Unified Huntington's Disease Rating Scale and Mini-Mental State Examination, and determined Huntingtin trinucleotide CAG repeat length." (PMID 22359536, 2012). "Cleavage of the full-length mutant huntingtin (mhtt) protein into smaller, soluble aggregation-prone mhtt fragments appears to be a key process in the neuropathophysiology of Huntington’s Disease (HD)." (PMID 22984513, 2012).
Huntington disease (continued). "Our studies have established that rapamycin treatment enhances the clearance of mutant huntingtin fragments, reduces aggregate formation and protects against toxicity in cell, Drosophila and mouse models of Huntington's disease (HD)." (PMID 21095248, 2012). "Our prior work identified PFN1 as an inhibitor of huntingtin aggregation, suggesting a role in the pathogenesis of Huntington Disease (HD)." (PMID 22479341, 2012). "For example, the Huntington's disease protein, huntingtin, is apparently cleaved into many different sized N-termninal fragments by many different proteases including caspases, calpains and a novel endopeptidase." (PMID 23028814, 2012). "Previous studies confirm that the mutant huntingtin difficult neurotrophic function of astrocytes leading to neuronal dysfunction in Huntington’s disease." (PMID 22919565, 2012). "This acetylation also mitigated the toxic effects of mutant huntingtin in primary striatal and cortical neurons and in a transgenic C. elegans model of Huntington's disease." (PMID 22518139, 2012). "For example, activation of autophagy by the mTOR (mammalian target of rapamycin) inhibitor rapamycin attenuates the accumulation of mutant huntingtin and is neuroprotective in a Drosophila model of Huntington’s disease." (PMID 22392734, 2012). "On the other hand, motility impairment has been shown in a model of Huntington’s disease in which mutant huntingtin interacts with the mitochondrial protein Drp1 and results in defective mitochondrial movement and synaptic deficiencies." (PMID 22392734, 2012). "One of the most common polyQ disorders, Huntington disease, is caused by exon I IT15 mutations that increase the number of CAG triplets, coding for Q in the huntingtin (htt) protein and develops at a probability proportional to the number of these repeats." (PMID 22253794, 2012). "Metabolic and psychiatric disturbances occur early on in the clinical manifestation of Huntington’s disease (HD), a neurodegenerative disorder caused by an expanded CAG repeat in the huntingtin (HTT) gene." (PMID 23251447, 2012). "BackgroundAbnormalities in brain cholesterol homeostasis have been reported in Huntington’s disease (HD), an adult-onset neurodegenerative disorder caused by an expansion in the number of CAG repeats in the huntingtin (HTT) gene." (PMID 23145355, 2012). "Understanding the mechanisms of clearance of toxic mutant huntingtin is essential in order to explore therapeutic strategies against Huntington's disease." (PMID 21631942, 2011). "The re-analysis of this dataset has revealed a strong network linking DISC1 and huntingtin protein, which is mutated in Huntington's disease, consistent with DISC1 and huntingtin regulating convergent pathways." (PMID 21298101, 2011). "Altered ERK1/2 and PDK1 phosphorylation have been described in Huntington's disease (HD), characterized by the expression of mutant huntingtin (mhtt) and striatal degeneration." (PMID 22041125, 2011). "In Huntington's disease, mutant huntingtin protein induces mitochondrial fragmentation and neuronal cell death." (PMID 21298101, 2011). "For instance, classifying sequences of huntingtin protein for induction of Huntington's disease critically relies on the length of a Glutamine repeat, an information that can be partly lost in sequence normalization." (PMID 21682849, 2011). "Toward this end, it has been shown that increasing autophagy by rapamycin administration decreases alpha-synuclein- and huntingtin-related neuropathologies in animal models of Parkinson and Huntington diseases, respectively." (PMID 21980451, 2011). "Here, we make use of modified 2′-O-methyl phosphorothioate (CUG)n triplet-repeat antisense oligonucleotides to effectively reduce mutant huntingtin transcript and protein levels in patient-derived Huntington's disease fibroblasts and lymphoblasts." (PMID 21909428, 2011).
Huntington disease (continued). "Recently, calpain has been implicated in the production of toxic fragments in two other diseases besides Alzheimer's disease: α-synuclein in Parkinson's disease and huntingtin in Huntington's Disease." (PMID 21858230, 2011). "In particular, low brain BDNF levels have been described in various neurodegenerative disorders, most notably, Huntington's Disease (HD), a progressive neurodegenerative disorder caused by a CAG trinucleotide expansion in the gene that encodes huntingtin." (PMID 21857974, 2011). "Huntington's disease (HD) is a hereditary neurodegenerative disease resulting from an expansion of the polyglutamine region of the ubiquitously expressed protein huntingtin (htt)." (PMID 21087849, 2011). "Chemical reduction of proteasome activity leads to an increase in the amount in huntingtin fragment levels and, in addition, proteasome activity has been show to decline with age, consistent with the late onset of Huntington’s disease." (PMID 21915392, 2011). "Huntingtin neurotoxicity suppressors identified through our screen also restored viability in an in vivo Drosophila Huntington's Disease model, making them attractive candidates for further therapeutic evaluation." (PMID 21909362, 2011). "For example, in Huntington's disease, the expansion of a glutamine stretch within the N-terminal region of huntingtin gene generates a protein with severe neurotoxic properties." (PMID 21808733, 2011). "To identify Huntington's Disease therapeutics, we conducted high-content small molecule and RNAi suppressor screens using a Drosophila primary neural culture Huntingtin model." (PMID 21909362, 2011). "Huntington Disease (HD) is a neurodegenerative disorder in which caspase activation and cleavage of substrates, including the huntingtin protein, has been invoked as a pathological mechanism." (PMID 21854568, 2011). "For example, a study reporting down-regulation of mTOR signaling in huntingtin-accumulating neurons in a mouse model of Huntington's disease at the same time showed that treating the mice with rapamycin was protective." (PMID 20862226, 2010). "Huntington's Disease is characterized by intraneuronal aggregates of polyglutamine-containing Huntingtin protein." (PMID 20126313, 2010). "For Huntington's disease, a transgenic rat model expressing a truncated huntingtin fragment with multiple CAG repeats was used." (PMID 20691122, 2010). "Geldanamycin has been demonstrated to activate a heat shock response and to suppress huntingtin protein aggregation in a cell culture model of Huntington's disease." (PMID 20090920, 2010). "Promoting mutant huntingtin clearance by activating macroautophagy is one approach for treating Huntington's disease (HD)." (PMID 20569486, 2010). "In the brains of Huntington's disease patients, for example, and mice expressing mutant huntingtin protein, a large percentage of parvalbumin-positive neurons selectively degenerate." (PMID 20678225, 2010). "In Huntington's disease (HD), mutant huntingtin (mHtt) disrupts the normal transcriptional program of disease neurons by altering the function of several gene expression regulators such as Sp1." (PMID 21179468, 2010). "For example, the mutant protein Huntingtin (Htt), which characterizes for Huntington's disease, contains a polyglutamine fragment which assists aggresome formation." (PMID 22649603, 2009). "Dysregulation of transcription as a result of mutant huntingtin expression showed a transcription signature replicating that reported in animal models and Huntington's disease patients." (PMID 19203385, 2009). "A promising area of research, as regards adenosine/BDNF cross talk, is Huntington’s disease, which has been associated with low BDNF levels in the cortical-striatal pathway, most probably due to a loss of function of mutated huntingtin." (PMID 20190960, 2009). "The exact physiological function of the normal Huntington disease (Hd) protein Huntingtin has yet to be elucidated." (PMID 19450442, 2009).
Huntington disease (continued). "Crucially, triggering of neuronal differentiation in mutant huntingtin expressing cell resulted in the appearance of additional pathological hallmarks of Huntington's disease including cell death." (PMID 19203385, 2009). "Accordingly, I selected a model protein unrelated to biogenesis of autophagic compartments (but otherwise known to be targeted into autophagosomes), namely, a poly-Q-expanded version of huntingtin, the protein involved in Huntington's disease." (PMID 19259979, 2009). "In neurodegenerative disorders, such as Huntington's disease and spinocerebellar ataxias, mutant proteins (huntingtin and ataxins respectively) containing expanded polyQ repeats form nuclear inclusions associated with proteasomes and HSP70 in neuronal cells." (PMID 19409099, 2009). "These new cell lines represent a reliable in vitro system for modeling Huntington's disease and should find wide use for high-throughput screening application and for investigating the biology of mutant huntingtin." (PMID 19203385, 2009). "In Huntington's disease, a polyglutamine expansion in the huntingtin protein triggers neuronal toxicity." (PMID 18454252, 2008). "Previous studies of Huntington's disease revealed an inverse relationship between the length of glutamine repeat of huntingtin and age of disease onset." (PMID 18666828, 2008). "In Huntington's disease, Huntingtin protein is thought to acquire gain of function due to expanded polyglutamine repeats." (PMID 18604272, 2008). "Wood and Morton recently showed that chronic lithium treatment improved motor function in a transgenic mouse model of Huntington disease (the R6/2 line) that expresses exon 1 of the human huntingtin gene with approximately 150 CAG repeats." (PMID 17535104, 2007). "It is interesting to note that lithium has produced beneficial effects in a cellular, Drosophila, and mouse model of Huntington disease toxicity in which fragments of polyglutamine expanded mutant huntingtin were expressed." (PMID 17535104, 2007). "Huntington's disease (HD) is an autosomal dominantly transmitted neurodegenerative disorder based on expansions of translated CAG repeats in the huntingtin gene beyond a threshold of 36 to >200 units." (PMID 16507108, 2006). "Huntington's disease (HD) is an inherited neurodegenerative disorder triggered by an expanded polyglutamine tract in huntingtin that is thought to confer a new conformational property on this large protein." (PMID 15649316, 2005). "Huntington's disease is an autosomal dominant neurodegenerative disease with a well-characterized genetic aetiology of a CAG expansion mutation in the huntingtin (HTT) gene, yet it remains without a cure." (PMID 41578740, 2026). "As this method is general, we anticipate that it could be applied to other amyloid fibrils implicated in neurodegenerative diseases, including tau (Alzheimer’s disease), huntingtin (Huntington’s disease), TDP-43 (ALS), and α-synuclein (Parkinson’s disease)." (PMID 41193694, 2026). "Both in vitro and in vivo work on the ubiquitin proteasome system, which is impaired in Huntington’s disease, can be stimulated by SF, leading to reduced accumulation of mutant huntingtin (mHtt) protein aggregates, the accumulation of which is a main cause of Huntington’s disease." (PMID 40284217, 2025). "Huntington’s disease (HD) is an autosomal dominant neurodegenerative disorder caused by an unstable expansion of CAG repeats in the HTT gene, leading to an elongated polyglutamine tract in the Huntingtin protein." (PMID 40908995, 2025). "Huntington’s disease (HD) is an autosomal-dominant neurodegenerative disorder of the central nervous system (CNS) resulting from an abnormal trinucleotide repeat expansion of cytosine-adenine-guanine (CAG) in the Huntingtin (HTT) gene." (PMID 41282737, 2025). "Similarly, in models of Huntington’s disease, Spt4 depletion selectively reduced trinucleotide repeats mRNA and polyQ mutant huntingtin protein levels." (PMID 41337098, 2025).